INS (insulin)
Diseases named in the same sentence as INS in open-access papers (continued):
Sharing a sentence is not in itself a finding about the gene and the disease.
Cognitive impairment (continued). "Furthermore, it was demonstrated that the treatment with intranasal insulin improves learning and memory in individuals with mild cognitive impairment (MCI) and AD, suggesting the involvement of dysfunctional insulin signaling as a key player in the pathogenic mechanism of AD progression." (PMID 31275224, 2019). "In sum, our study demonstrates that the protein tau is a crucial downstream target of the insulin pathway, and mediates the cognitive deficits observed in T1DM mouse models, whereas in T2DM mice, other factors such as chronic inflammatory may be responsible for cognitive deficits." (PMID 30809950, 2019). "Thus, dysregulation or resistance to central insulin action could result in impaired cognition, and indeed, recent work suggests that insulin is the common link between metabolic disorders and disorders of cognition." (PMID 30568606, 2018). "Furthermore, these data suggest that insulin may act to attenuate high fat diet induced cognitive deficits by reducing neuroinflammation." (PMID 30619085, 2018). "Furthermore, intranasal insulin also prevented the short-term cognitive impairment in aged mice." (PMID 28539885, 2017). "It is possible that a patient's cognitive impairment may have been recognized by a family member and/or a healthcare provider, who could have taken steps to ensure that the insulin was administered under supervision, leading to greater persistence among the patients with cognitive impairment." (PMID 27761472, 2016). "This concept is corroborated by the findings that cognitive impairment and neurodegeneration can be slowed, reduced in severity, or prevented in experimental animals and humans by treatment with insulin sensitizer agents, insulin, or long-acting glucagon-like peptide-1 (GLP-1)-related compounds." (PMID 25035815, 2013). "Since Aβ and p-tau, key AD hallmarks, are influenced by IR and insulin signaling components (P-AKT and p-mTOR), this explains the strong link between IR and AD, as well as the cognitive impairment observed in stressed rats during behavioral assessment." (PMID 40397120, 2025). "To further assess FCGR2B silencing on DM-induced cognition impairment, we tested the body weight, the FBG and the insulin level." (PMID 40537751, 2025). "Building upon the background above and our research achievements, we tested the effect of intranasal treatment with a new nanoformulation containing melatonin, insulin, and THC on AD-related cognitive impairment and pathologic changes using an AD mouse model." (PMID 36830601, 2023). "In two independent cohorts of post-mortem brain samples isolated from individuals with AD or mild cognitive impairment (MCI), substantial abnormalities were described in the basal activation of insulin signaling." (PMID 36670973, 2023). "Consequently, the evaluation of serum proinsulin levels may offer a valuable tool for identifying non-diabetic individuals with cognitive impairment who could benefit from emerging Alzheimer’s treatments associated with the insulin pathway, such as GLP1-RA." (PMID 38105338, 2023). "Three months after 6-OHDA treatment, cognitive deficit was accompanied by decreased AMPAR activity and TH levels (HPC, S), while levels of the proteins involved in insulin signaling remained largely unchanged." (PMID 36979662, 2023). "Depletion of insulin in these mice by administration of STZ has been shown to increase Aβ accumulation in the brain, which leads to cognitive impairment." (PMID 35701718, 2022). "Similarly, insulin metabolism, protein metabolism, mitochondrial function, and systemic inflammation have been suggested to be altered in individuals with low skeletal muscle mass and may contribute to the development of cognitive impairment." (PMID 35661882, 2022). "In patients with mild cognitive impairment (MCI) or AD, a single dose of intranasal insulin improves memory, and intranasal insulin also improves memory with multiple treatments of patients with AD or MCI." (PMID 35631378, 2022).
Cognitive impairment (continued). "Furthermore, impaired central insulin signaling manifests similar pathology to that of early AD including neuroinflammation accompanied by deficits in synaptic plasticity and episodic memory, suggesting overlapping mechanisms of central insulin resistance and early AD‐like cognitive impairment." (PMID 33382528, 2021). "Investigating the use of intranasal insulin (INI) as a novel treatment option in patients with AD and mild cognitive impairment (MCI) provided clinical evidence of the safety and efficacy of targeting insulin signaling therapeutically in neurodegeneration." (PMID 33925119, 2021). "Following the notion that central insulin seems to have a positive effect on cognition, small clinical trials on INI for the treatment of mild cognitive impairment (MCI) and mild AD have been performed." (PMID 33917464, 2021). "Insulin-induced GLUT4 translocation to the neuronal membrane in the hippocampus occurs during periods of high energy demand, such as during learning, suggesting that deregulation of insulin-dependent glucose transport in several brain regions may be a cause of cognitive impairment." (PMID 33810179, 2021). "The dysregulated insulin signaling in the hippocampus activated microglia and astrocyte, decreased BDNF levels, and inhibited neurogenesis, leading to cognitive deficits." (PMID 34108878, 2021). "Also, oxidative stress linked with elevated cholesterol uptake impairs insulin signaling, enhances serine phosphorylation of IRS1, and inhibits insulin-induced PI3K and AKT activities, resulting in enhanced stress-induced JNK activity that increases cognitive impairments in mice." (PMID 34118939, 2021). "In two independent cohorts of post-mortem brains samples collected from AD or mild cognitive impairment (MCI) subjects, consistent defects in the basal levels and/or activation of proteins belonging to insulin signaling were described." (PMID 32733190, 2020). "This concept describes a brain-specific pathological situation in which insulin and IGF resistance is developed inducing cognitive impairments and neurodegeneration." (PMID 31551756, 2019). "Furthermore, early treatment to reduce insulin sensitivity may prevent cognitive impairment." (PMID 31661025, 2019). "Moreover, the role of insulin signaling in mediating cognitive deficits after TBI remains unknown, thus a more complete understanding of these phenomena will be necessary in order to establish a treatment plan targeting central metabolic processing in TBI patients." (PMID 30202553, 2016). "Hippocampal-dependent cognitive deficits induced by HFD have been attributed to leptin, calcium dysregulation, inflammation, cellular stress, and impaired insulin signaling." (PMID 27676071, 2016). "Hence, the combination of inflammation, neuronal insulin resistance, oxidative/ER stress and translational repression might generate a noxious scenario of brain metabolic stress to mediate and propagate synapse defects, resulting in cognitive deficits." (PMID 26042036, 2015). "Although insulin is known to enhance cognitive performance in non-T2DM, the connection between hyperinsulemia and cognitive impairment in T2DM is unclear." (PMID 24816647, 2014). "The pivotal roles of insulin and IGF-1 resistance as mediators of cognitive impairment and neurodegeneration have been well documented in humans and experimental animals." (PMID 25035815, 2013). "On the other hand, intraperitoneal insulin does not seem to ameliorate cognitive impairment in Aß25-35-injected rats in the MWM neither in APP/PS1 in the Barnes maze." (PMID 41146261, 2025). "Targeting metabolic- and plasticity- related systems by augmenting insulin and IGF-1 signaling may be considered a therapeutic strategy for reducing AUD-related cognitive deficits." (PMID 41400881, 2025). "This is not the case over the age of 90, when a negative correlation between insulin and cognitive impairment arises, suggesting its protective property in this age group." (PMID 38542318, 2024).
Cognitive impairment (continued). "As a consequence, the weakening of insulin signaling in the brain, for example, in the conditions of neuron-specific knockout of INSR and IRS-2, promotes hyperphosphorylation of the tau protein and provokes neurodegeneration and cognitive deficit." (PMID 36834685, 2023). "By shifting APP processing to non-amyloidogenic pathways, intranasal insulin improved cognitive impairments and decreased brain Aβ levels and Aβ plaque deposition in APP/PS1 mice." (PMID 36909158, 2023). "These abnormalities were negatively correlated with global cognition and memory scores regardless of Aβ and Tau levels, suggesting that brain insulin resistance contributes to cognitive impairment independently from AD neuropathology." (PMID 36670973, 2023). "Hypothalamic–pituitary–adrenal (HPA) axis hyperfunction is prevalent in dementia and other cognitive disorders, which might be the reason for higher adrenocorticotropic hormone (ACTH) and glucocorticoid (GC) levels, resulting in insulin resistance." (PMID 37214403, 2023). "When insulin signal transduction was impaired, AKT lost its inhibition of glycogen synthase kinase-3β (GSK3β), increased the expression of Aβ and Tau, and further aggravated cognitive impairment." (PMID 37152933, 2023). "The positive impact of intranasal insulin was initially explored in individuals without cognitive impairment." (PMID 37374288, 2023). "Patients in the cognitive impairment group were significantly older, lower educated and had lower frequencies of metformin usage and higher frequencies of history of stroke or insulin usage than those in no cognitive impairment group (P <0.05)." (PMID 35992100, 2022). "In summary, our results indicate that GMT can alter cognitive deficits and Aβ deposition in ZDF rats, effects that may be achieved through improved insulin resistance and leptin resistance." (PMID 35721013, 2022). "Patients with cognitive impairment were more likely to be on multiple insulin injections - 90 (75%), when in the group without cognitive impairment most received insulin on a pump regimen -24 (80%)." (PMID 36105393, 2022). "Our results suggest that hypertriglyceridemia reduces the cognitive benefit of adipocytokines in older adults without cognitive impairment and with high insulin sensitivity." (PMID 34731089, 2021). "In summary, our results suggested that insulin resistance but not β-cell function was increased in patients with cognitive impairment alone and those with both cognitive impairment and solid cancer than in cancer patients without cognitive impairment." (PMID 31661025, 2019). "Additionally, we recently reported an immunoepigenetic signature of cognitive impairment in monocytes from HIV-infected individuals with dementia, prompting us to examine whether altered DNA methylation states in these cells may also relate to insulin resistance and cardiometabolic disease risk." (PMID 31253200, 2019). "Although it takes from 10 to 15 years after Aβ starts to aggregate to observe cognitive impairments in AD patients, an acute effect of Aβ upon cognition cannot be ruled out, especially taking into account the disruption in insulin signaling." (PMID 29743868, 2018). "In conclusion, insulin and IGF-1 may alleviate cognitive impairment in PD via the inactivation of GSK3β mediated by PI3K/Akt." (PMID 29515352, 2018). "Conversion from mild cognitive impairment (MCI) to AD is higher in individuals with impaired glycemia compared to normoglycemic patients, suggesting that baseline glycemia and insulin resistance play key roles on cognitive decline and AD progression." (PMID 29743868, 2018). "We demonstrate an association between a persistent neuronal DDR, increased cholesterol biosynthesis, impaired insulin/IGF and Wnt signalling, and increased GSK3β, which may contribute to neuronal dysfunction and cognitive impairment." (PMID 26095650, 2016).
Cognitive impairment (continued). "Taken together, these studies add to the growing and compelling evidence of the contribution that insulin sensitivity may have in mediating both TBI-induced pathophysiology and the resulting cognitive deficits." (PMID 30202553, 2016). "This is of importance not least because intranasal insulin administration targeting the brain emerged as promising intervention for the treatment of cognitive impairment." (PMID 27589235, 2016). "Based on the encouraging effects of intranasal insulin that demonstrated improvement of memory without any side effects in healthy humans, few clinical trial have been carried out in patients with mild cognitive impairments (MCI) and AD patients." (PMID 26136647, 2015). "The R6/2 mice exhibited cognitive impairments and deficits in the replication of β cells and insulin secretion, which indicates that HD is expressed not only in neurons but also in the pancreatic islets." (PMID 26075247, 2015). "Since aberrant insulin signalling was widely observed in T2DM, this perturbation could be contributing to cognitive impairment." (PMID 24816647, 2014). "In fact, cognitive impairment does not significantly affect adherence to oral medications or self-care in patients with T2D, rather injections including insulin might be a problem." (PMID 39049060, 2024). "Our results may indicate early neurodegenerative processes in AD-related cortical regions transpiring in the midlife population with higher visceral adiposity and insulin resistance, even without any overt cognitive impairment." (PMID 37548931, 2024). "Previous animal research suggested that metformin might improve cognitive impairment by reversing the adverse consequences of poor insulin signaling, which generates a cascade of negative events such as inflammation and tau hyper-phosphorylation." (PMID 38139841, 2023). "Therefore, MACs might possess the potential to combat diet-induced cognitive impairment by inhibition of PTP1B expression, restoration of insulin signaling, and Tau neuronal proteins for synaptogenesis in the hippocampus." (PMID 32127019, 2020). "There were also no participants with significant cognitive impairments, who may benefit the most from the insulin treatment." (PMID 31022213, 2019). "Thus, studies conducted in the last 20 years support the hypothesis that deficits in brain insulin and insulin-like growth factor (IGF-1) signaling mediate cognitive impairment and neurodegeneration in AD." (PMID 31551756, 2019). "Since 11β-HSD1 increases local corticosterone levels, it may further contribute to cognitive impairments in T1D in addition to the lack of insulin and to dysregulated systemic corticosterone levels." (PMID 28458655, 2017). "Unexpectedly, in aged rats, the responsiveness to insulin was completely absent, that is, spatial memory was still impaired suggesting that an age-dependent insulin resistance may contribute to the cognitive impairment observed in neurodegenerative diseases." (PMID 25889938, 2015). "To investigate the role of CCH in AD-related brain abnormalities and cognitive impairment, we performed UCCAO in adult mice and then studied general and memory behavior, O-GlcNAcylation, tau phosphorylation, synaptic proteins, hexosamine biosynthetic pathway (HBP) and insulin signaling." (PMID 24575038, 2014). "Thus, the regulation of insulin signaling and CREB/BDNF pathways in the hippocampus via SCFAs, particularly butyrate, was proposed as the mechanism by which the combination of hesperetin and metformin improved cognitive impairment in DM rats through the gut–brain–microbiota axis." (PMID 40076550, 2025). "However, whether the pretreatment with intranasal insulin can also prevent anesthesia-induced cognitive impairment had not been studied." (PMID 26879001, 2016).
Cognitive impairment (continued). "Similarly, while the mechanisms of cognitive impairment in human diabetics have not been well defined, it has been established that both type-1 and type-2 diabetics exhibit these impairments, despite strikingly different patterns of insulin secretion and insulin sensitivity." (PMID 26823968, 2016). "A comprehensive proteomic study of platelets in patients with T2DM and mild cognitive impairment (T2DM-MCI) versus those without (T2DM-nMCI) revealed that differentially expressed proteins are primarily involved in amyloidosis, mitochondrial autophagy, and insulin signaling pathways." (PMID 40171533, 2025).